ENSG00000202231
Synonyms: LOC124900498
Gene: Small nucleolar RNA gene on chromosome X (100,822,620 to 100,822,752, reverse strand). Ensembl gene ENSG00000202231.
Gene Ontology:
Biological process: RNA processing
Cellular component: nucleolus
Homologues: Paralogues in human: SNORA9 (94% identical), SNORA9B (90% identical).